DMD (dystrophin)
Diseases named in the same sentence as DMD in open-access papers (continued):
Sharing a sentence is not in itself a finding about the gene and the disease.
cardiomyopathy (continued). "DMD-CMs were chosen over other cardiomyopathy models because the lack of full-length dystrophin in diseased cardiomyocytes may directly affect the interaction of cardiac cells with the extracellular environment." (PMID 36419836, 2022). "Therefore, our findings suggest very concrete new avenues of research into a new molecular link between dystrophin and activation of cardio-protective mechanisms that are relevant to DMD cardiomyopathy, and more generally to physiological and pathological cardiac remodeling." (PMID 33949649, 2021). "Since cardiomyopathy due to the absence of dystrophin is more manifested with advancing age in patients and canine models, pig models may also display histological and functional abnormalities in the heart later during life." (PMID 34884867, 2021). "Furthermore, transgenic expression of a mechanically functional dystrophin, but not dystrophins lacking the DGC- or actin-binding regions, are able to prevent cardiomyopathy onset, further supporting the relevance of dko cardiomyopathy to DMD." (PMID 33651713, 2021).
dilated cardiomyopathy (66 papers, 2009 to 2026). Cardiomyopathy which is characterized by dilation and contractile dysfunction of the left and right ventricles. "We report an early presentation of dilated cardiomyopathy in a 33-year-old woman due to a de novo pathogenic variant of the dystrophin (DMD) gene (p.Asp3368Gly)." (PMID 38474032, 2024). "In human literature, dilatated cardiomyopathy is associated with mutation of dystrophin and tafazzin, cardiac actin, desmin and laminin A/C and also the sarcoglycans, in particular delta-sarcoglycan." (PMID 37628692, 2023). "Loss of dystrophin staining can be considered as one of the markers of cardiac hypertrophy and early heart failure and loss of dystrophin immunostaining was observed in enterovirus-induced dilated cardiomyopathy in humans." (PMID 34063460, 2021). "The incidence of skeletal muscle damage among female carriers of loss-of-function DMD mutations, including asymptomatic carriers, was reported as between 2.5% and 19%, and the incidence of dilated cardiomyopathy as between 7.3% and 16.7%." (PMID 34796900, 2021). "Cardiac symptoms are particularly prevalent in female dystrophin mutation carriers, affecting about 8% of this population with dilated cardiomyopathy (DCM) as a common presentation." (PMID 32650403, 2020). "Mutations in the MYH6 gene are associated with hypertrophic as well as dilated cardiomyopathy, frequently associated with DMD." (PMID 32927262, 2020). "Mutations in the DMD gene (encoding dystrophin) account for 2% of inherited dilated cardiomyopathy (DCM)." (PMID 32477154, 2020). "DMD is an X-linked recessive disease caused by mutations of the dystrophin gene that affects muscular functions and strength and accompanying dilated cardiomyopathy." (PMID 32508664, 2020). "Research in the 1990s showed that dystrophin was important in canine X-linked muscular dystrophy and dilated cardiomyopathy." (PMID 29367539, 2017). "Symptomatic female DMD carriers display 10–20 times higher than normal creatine kinase (CK) levels and dystrophin-associated dilated cardiomyopathy." (PMID 25775477, 2015). "Similarly, cardiac involvement is also a hallmark of MDs, particularly in Duchenne and Becker, where dystrophin deficiency leads to dilated cardiomyopathy." (PMID 41302960, 2025). "Reported incidence rates of skeletal muscle damage among female carriers (including those who are asymptomatic) range from 2.5 % to 19 %, while the prevalence of dilated cardiomyopathy is 7.3 %–16.7 % in carriers of DMD-causing variants and 0 %–13.3 % in carriers of BMD-causing variants." (PMID 41321997, 2025). "Calcium handling abnormalities have been described as a major consequence of dystrophin and other dilated cardiomyopathy (DCM)-related mutations, but the mechanisms linking dystrophin deficiency to abnormal calcium cycling remain unclear." (PMID 36419836, 2022). "The described ion channel abnormalities in cardiomyocytes derived from dystrophin-deficient DMD/BMD mouse models may represent a primary effect of the dystrophin gene mutation and precede dilated cardiomyopathy development." (PMID 30360568, 2018). "For example, do some pathogenic variants in DMD cause isolated dilated cardiomyopathy (DCM)?" (PMID 27446933, 2016). "Protease 2A is one of the picornaviral proteinases responsible for cleavage of the host cell protein eIF4G, polyprotein and maybe dystrophin, a key protein component of heart muscle that is frequently mutated in inherited forms of dilated cardiomyopathy." (PMID 22039449, 2011). "Protease 2A is responsible for cleavage of the host cell protein eIF4G, polyprotein and maybe dystrophin, a key protein component of heart muscle that is frequently mutated in inherited forms of dilated cardiomyopathy." (PMID 22039449, 2011). "Indeed, a deficiency in dystrophin results in the progressive degeneration of skeletal muscle and severely compromises the structure and function of cardiomyocytes, eventually leading to dilated cardiomyopathy and heart failure." (PMID 41923738, 2026).
dilated cardiomyopathy (continued). "However, studies have identified potential risks associated with excessive micro-dystrophin expression in the heart, which may lead to dilated cardiomyopathy and heart failure due to competition with native utrophin and protein degradation pathway overload." (PMID 40332074, 2025). "We presented the case of a DMD patient with a deletion in exon 55 of the dystrophin gene, highlighting an instance of early-onset dilated cardiomyopathy." (PMID 40004149, 2025). "We showed that a single injection in young dKO mice induced the expression of micro-dystrophin in the heart and prevented the development of dilated cardiomyopathy." (PMID 40562489, 2025). "In female DMD carriers, the prevalence of elevated CK was approximately 53%, skeletal muscle injury was approximately 2.5–19%, and dilated cardiomyopathy was approximately 7.3–16.7%." (PMID 37254189, 2023). "The absence of dystrophin protein in the heart results in these patients invariably developing dystrophin-deficient cardiomyopathy (DDC), mainly in the form of dilated cardiomyopathy (DCM) with congestive heart failure (CHF) and rhythm disturbances." (PMID 33396334, 2020). "Early dilated cardiomyopathy was present in one (1.5%) DMD proband who has two similarly affected older brothers." (PMID 29847600, 2018). "This review gives an overview of the work carried out in cardiac troponin T and dystrophin to date in both human and animal dilated cardiomyopathy." (PMID 29367539, 2017). "Cardiac troponin T and dystrophin were observed to be associated with both human and turkey (troponin T) and canine (dystrophin) dilated cardiomyopathies." (PMID 29367539, 2017). "This study indicates that approximately 28% dystrophin restoration is sufficient to prevent the onset of exercised-induced dilated cardiomyopathy and maintain cardiac function." (PMID 25758104, 2015). "In various study populations the incidence of dilated cardiomyopathy (DCM) among DMD carriers varied between 7% to 9%, and among BMD carriers from 0% to 13%." (PMID 23870371, 2013). "The overexpression of micro-dystrophin in cardiac tissue may also lead to adverse outcomes, like dilated cardiomyopathy, possibly due to competition with endogenous utrophin or protein degradation overload." (PMID 40332074, 2025). "Dilated cardiomyopathy is one of the lethal causes of DMD, and studies have used CRISPR Cpf1 to edit DMD mutations in patient‐derived iPSCs as well as mouse models to restore antimorphic protein expression by skipping out‐of‐frame DMD exons or correcting nonsense mutations." (PMID 39081515, 2024). "Mutations in the DMD gene are causing DMD, BMD, and dilated cardiomyopathy." (PMID 37374149, 2023). "Indeed, dystrophin cleavage is a well-known mechanism of EV-B pathogenicity inducing dilated cardiomyopathy, whereas insulin production decrease is the first step of type 1 diabetes development." (PMID 36016091, 2022). "Accordingly, dystrophin staining was used to test whether there are abnormalities in our genetically modified rats and dystrophin immunostaining disruption suggests dilated cardiomyopathy." (PMID 34063460, 2021). "Despite being deficient for dystrophin, mdx mice display overall minimal clinical symptoms; their lifespan is only reduced by ≈25% (vs. 75% decrease in humans) without obvious signs of dilated cardiomyopathy." (PMID 33255644, 2020). "It is known that about 8% of carriers present with dilated cardiomyopathy, though it may vary from 0% to 16.7%, depending on if the carrier is classified as having DMD or BMD." (PMID 32650403, 2020). "Mutations in the dystrophin gene at the Xp21.1 locus are associated with devastating X-linked skeletal muscle disorders, such as Duchenne or Becker muscular dystrophies (DMD/BMD), and account for <2% of dilated cardiomyopathy (DCM) cases." (PMID 32477154, 2020). "Mdx mice, which have the same dystrophin mutation as human patients, are of limited use, as they do not develop early dilated cardiomyopathy as seen in patients." (PMID 29479480, 2018).
dilated cardiomyopathy (continued). "Similarly, in humans, most female DMD carriers are asymptomatic, but up to 20% exhibit mild to moderate muscle weakness and 8% have dilated cardiomyopathy." (PMID 29474464, 2018). "Taken together, all these data reveal that a common mitochondria-mediated signaling network underlies enhanced apoptosis in DMD iPSC-CMs, which could account for dilated cardiomyopathy in DMD patients with a Rod-region-specific dystrophin gene deletion." (PMID 25791035, 2015). "However, about 8–18% of carrier girls present with dilated cardiomyopathy, which could vary to certain degree depending on whether the carrier girl manifests a DMD or BMD phenotype." (PMID 37759719, 2023). "Severe dilated cardiomyopathy with refractory heart failure accounts for the highest number of deaths in patients with BMD and DMD." (PMID 38791328, 2024). "The picture of severe dilated cardiomyopathy with intractable heart failure is typical of BMD XL-DCM and DMD/BMD carriers and frequently observed in patients with DMD over the age of 18." (PMID 38791328, 2024). "However, carriers of Dystrophin gene mutations may represent a rare distinct form of dilated cardiomyopathy without skeletal muscle abnormalities." (PMID 37759719, 2023). "Consistently, DMD protein level is reduced in DOT1L-ablated hearts, which displays dilated cardiomyopathy." (PMID 34568453, 2021). "The dilated cardiomyopathy (DCM) pathway involves proteins such as Desmin, DMD, Titin, Tnt, ACTA1, TPM, Laminac, SGCD, TNF-α, IGF-1, TGF-β, and Ang-II." (PMID 32419790, 2020). "A similar 5’ duplication involving DMD exons 2-7 has been reported in a human family with dilated cardiomyopathy but without skeletal myopathy." (PMID 36041985, 2022). "Somatic mosaicism for DMD should be considered in acute heart failure with dilated cardiomyopathy, as genetic normalization in heart is unlikely to occur." (PMID 19530190, 2009). "The lack of dystrophin in some heart muscle fibers reflects damage due to dilated cardiomyopathy." (PMID 34063460, 2021). "Interestingly, heterozygous carriers of dystrophin defects have no skeletal muscle disease, but they show dilated cardiomyopathy." (PMID 19333401, 2009). "A follow-up study on female BMD/DMD carriers reported that only 1 BMD carrier and 10 DMD carriers of a total of 99 DMD/BMD carriers developed dilated cardiomyopathy (DCM) during a 9-year follow-up period, and none of BMD carriers died." (PMID 37426526, 2023). "There was no dilated cardiomyopathy noted in this case, which would be an unusual presentation for BMD or DMD because dilation becomes more apparent with age in both of these." (PMID 33344329, 2020).
heart failure (53 papers, 2009 to 2026). Inability of the heart to pump blood at an adequate rate to meet tissue metabolic requirements. "The treatment of women with the DMD mutation follows the same guidelines for patients with heart failure." (PMID 39075955, 2024). "Although females possessing heterozygous DMD mutations (DMD carriers) rarely exhibit clinical symptoms, they can sporadically develop muscle weakness and heart failure." (PMID 37772130, 2023). "It is caused by mutations in the DMD gene and is characterized by progressive muscle degeneration that results in loss of function and early death due to respiratory and/or cardiac failure." (PMID 36694468, 2023). "DMD and BMD result from the loss of a functional dystrophin protein, and the leading cause of death in these patients is cardiac remodeling and heart failure." (PMID 35887128, 2022). "The stabilization of the DGC throughout heart failure evolution in Fiona/dko mice will allow future investigations to define underlying cellular pathological mechanisms involving dystrophin and its interacting proteins." (PMID 33651713, 2021). "It was reported in rats that early dystrophin loss in cardiomyocytes is coincident with the transition of compensated cardiac hypertrophy to heart failure." (PMID 34063460, 2021). "Our findings associate genetically derived heart failure in a dystrophin-deficient patient with decreased c-kit+/CD45− CVPCs and their resilience, possibly hinting at a lack of cardioprotective capability and/or reduced homeostatic support." (PMID 32138751, 2020). "Myocardial involvement shown as LGE in CMR occurs in a substantial number of DMD carriers; it is associated with clinical and morphometric signs of incipient heart failure." (PMID 27660108, 2016). "The cardiac improvement observed when P2RX7 was blocked is also of clinical importance because, with prolonged patient survival (due to advances in general care), heart failure becomes a more common cause of death in DMD." (PMID 26461208, 2015). "A F2 chicken that showed cardiomegaly and succumbed to heart failure had the kDNA mutation in an exon of the dystrophin gene (FR681733)." (PMID 21468314, 2011). "The severity of muscle wasting in DMD means that most patients die in the second decade of their lives due to respiratory and cardiac failure, as a consequence of loss of dystrophin expression in both cardiac and skeletal muscle." (PMID 20020055, 2009). "GRMD dogs harbor a mutation in the dystrophin gene resulting in a loss of dystrophin protein in striated muscles and display dystrophic muscle lesions, progressive fibrosis, early locomotor impairment, and premature death due to respiratory or cardiac failure." (PMID 38044436, 2023). "Interestingly, heart failure and skeletal muscle weakness were directly associated with the kDNA mutations and rupture of the dystrophin gene in chromosome 1 of adult chickens." (PMID 21468314, 2011). "Interestingly, documented clinic and pathologic manifestations were clearly associated with the kDNA-mutations in the locus of the dystrophin gene in two chickens with muscle weakness, cardiomegaly and heart failure." (PMID 21468314, 2011). "The importance of dystrophin loss to the development of heart failure has also been demonstrated through the antisense therapeutic dystrophin that restores to almost normal levels the dystrophin expression in the cardiac muscle and prevents the development of cardiac failure in dystrophic mdx mice." (PMID 29267303, 2017). "Patients with DMD lack functional dystrophin protein due to the deletions of dystrophin gene, leading to weakening muscle and death from respiratory or cardiac failure." (PMID 39910928, 2025). "Clinical trials with heart failure drugs and gene therapy for DMD carriers are also needed to evaluate their efficacy and safety, with a positive impact on survival." (PMID 39075955, 2024).
heart failure (continued). "Similarly, mitochondrial function and biogenesis were found compromised in cardiomyocytes from the Duchenne mouse model mdx with “humanized” telomeres suggesting that mitochondrial dysfunction accompanies dystrophin loss and may account for the etiology of dystrophic heart failure." (PMID 37501163, 2023). "Authors showed for the first time that micro-dystrophin effectively prevents cardiac failure in mouse." (PMID 35419381, 2022). "Approximately 10–20% of DMD patients die from heart failure or sudden death because of progressive heart disease, which is a significant cause of patient death, along with respiratory failure." (PMID 35887128, 2022). "We used this model to test micro-dystrophin gene therapy efficacy on heart failure prevention for the first time." (PMID 33651713, 2021). "In support of the current findings, Taub and colleagues have previously shown that muscles from diabetics and heart failure patients have very low levels of dystrophin protein." (PMID 32358862, 2020). "Patients with BMD and XLCM often have sufficient dystrophin expression to display mild skeletal muscle pathology, but BMD has a high risk of heart failure, and XLCM patients succumb to heart failure between 10 and 20 years of age." (PMID 31443395, 2019). "Standard medical treatment for heart failure has been successfully implemented in DMD patients, whereas data on the effectiveness of the same medication in DMD carriers are insufficient." (PMID 27660108, 2016). "The reversal of heart failure (myocardial recovery), by means of mechanical circulatory assistance, was indicated by the normalization of dystrophin expression and integrity." (PMID 22347659, 2011). "The changes in dystrophin expression in our pilot study were consistent with the development of heart failure and subsequent recovery after LVAD placement in humans." (PMID 22347659, 2011). "Another cellular marker of heart failure is dystrophin, a protein that connects the extracellular matrix with the sarcomere via actin." (PMID 22347659, 2011). "The degree of remodeling was indicated by the disruption of dystrophin expression, as well as hemodynamic, echocardiographic, histologic, molecular, and clinical signs of heart failure." (PMID 22347659, 2011). "It is estimated that about 75% of DMD patients die due to respiratory failure and about 20% of them due to heart failure." (PMID 20492678, 2010). "The most common cause of death for patients with DMD is cardiac failure due to the lack of dystrophin in cardiomyocytes." (PMID 40493400, 2025). "In this study, we found that lncDach1 was increased during heart failure, indicating that it may contribute to sodium channel remodeling and arrhythmogenesis during heart failure by interfering with the action of dystrophin." (PMID 39773412, 2025). "Female DMD carriers occasionally exhibit symptoms such as muscle weakness and heart failure." (PMID 37772130, 2023). "No dystrophic animal model previously existed that reproducibly progressed into heart failure, so the ability of micro-dystrophin delivered postnatally to prevent heart failure is unknown." (PMID 33651713, 2021). "However, no mouse models progressed into heart failure, and dog models showed highly variable progression insufficient to evaluate efficacy of micro-dystrophin or other therapies on DMD heart failure." (PMID 33651713, 2021). "We showed that decreased expression of dystrophin and increased expression of calpains are coincident and could work as possible therapeutic targets to prevent heart failure as a consequence of cardiac hypertrophy." (PMID 29267303, 2017). "In this study, we showed that decreased expression of dystrophin and increased expression of calpains are coincident and could work as possible therapeutic targets to prevent heart failure as a consequence of cardiac hypertrophy." (PMID 29267303, 2017).